DAP3 (death associated protein 3)
Description:
As a component of the mitochondrial small ribosomal subunit, it plays a role in the translation of mitochondrial mRNAs. Involved in mediating interferon-gamma-induced cell death. Displays GTPase activity in vitro.
Synonyms: MRP-S29; S29mt; DAP-3; MRPS29; bMRP-10; MGC126058; MGC126059; DKFZp686G12159; mS29; PRLTS7
Tractability: Small molecule: a structure with a bound ligand is known. PROTAC: ubiquitination databases record sites on it; its protein half-life has been measured.
Target class: Other cytosolic protein
Gene: Protein-coding gene on chromosome 1 (155,687,833 to 155,739,014, forward strand). Ensembl gene ENSG00000132676.
Subcellular location: Mitochondrion
Subcellular location (Human Protein Atlas): Mitochondria; Nucleoplasm
Pathways (Reactome):
Metabolism of proteins: Mitochondrial ribosome-associated quality control; Mitochondrial translation elongation; Mitochondrial translation initiation; Mitochondrial translation termination
Gene Ontology:
Molecular function: GTPase activity; protein binding; RNA binding; structural constituent of ribosome
Biological process: mitochondrial translation; apoptotic signaling pathway; apoptotic process
Cellular component: mitochondrion; nucleoplasm; mitochondrial inner membrane; mitochondrial small ribosomal subunit; mitochondrial matrix; mitochondrial ribosome; small ribosomal subunit
Genetic constraint (gnomAD): Loss-of-function variants: 26 observed, 51.06 expected, observed/expected ratio (o/e) 0.51, 90% interval 0.37 to 0.71. The upper end of that interval is the gene's LOEUF score, 0.71, which puts it in group 2 of 6, group 1 being the genes least tolerant of losing a copy. Missense variants: 446 observed, 491.92 expected, observed/expected ratio (o/e) 0.91, 90% interval 0.84 to 0.98. Synonymous variants: 165 observed, 175.57 expected, observed/expected ratio (o/e) 0.94, 90% interval 0.83 to 1.07.
Homologues: Orthologues: chimpanzee DAP3 (99% identical), macaque DAP3 (91% identical), pig DAP3 (88% identical), rabbit DAP3 (86% identical), guinea pig DAP3 (86% identical), dog DAP3 (83% identical), mouse Dap3 (81% identical), rat Dap3 (79% identical), tropical clawed frog dap3 (58% identical), zebrafish dap3 (57% identical), Drosophila melanogaster mRpS29 (37% identical), Caenorhabditis elegans dap-3 (30% identical).
Diseases named in the same sentence as DAP3 in open-access papers:
DAP3 is named in the same sentence as 42 diseases in open-access papers, as found by Europe PMC text mining. Sharing a sentence is not in itself a finding about the gene and the disease. The quoted sentences say what the papers report.
breast carcinoma (8 papers, 2015 to 2024). "In a clinical cohort study, significant correlations between DAP1 and DAP3 were found in breast cancer, another study reported that the expression patterns of DAP3 and heat shock protein 90 (HSP90) were similar." (PMID 38352299, 2023). "In contrast, the levels of DAP3 are low in gastric cancer and breast cancer compared with the adjacent normal tissues." (PMID 38352299, 2023). "It was reported that DAP3 was upregulated in pancreatic cancer, breast cancer and correlated with malignant phenotypes." (PMID 36686684, 2022). "On the other hand, our group has published a clinical study, in which we examined the mRNA expression of DAP3 in a breast cancer cohort of 127 patients, with a median follow-up of 10 years." (PMID 25883535, 2015). "According to these network analyses, it is suggested that MRPS30 may play a role in the apoptosis process and breast cancer development through interaction with DAP3, MLPL37, and MRPL28." (PMID 38886335, 2024). "have recently reported that a DAP3 knockdown can inhibit the growth of breast cancer cells." (PMID 37023702, 2023). "However, DAP3 silencing in breast cancer cells led to enhanced tumor progression, including increased adhesion, migration, and invasion." (PMID 38352299, 2023). "Increased expression levels of DAP3 have been observed in invasive glioblastoma as well as glioma cells with induced migratory phenotype, while an inverse association between DAP3 expression and clinical outcome has been found in breast cancer, corresponding to the pro-apoptotic function of DAP3." (PMID 34026765, 2021). "Further investigations would be required to characterise the role of DAP3 in human breast cancer." (PMID 25883535, 2015). "Furthermore, subgroup analysis showed a substantial impact of DAP3 on the prognosis of breast cancer subtypes, except for basal cell-like subtypes, estrogen receptor-negative subtypes, and human epidermal growth factor receptor-2 overexpression subtypes (P < 0.05)." (PMID 38352299, 2023). "Further analysis using the Gene Expression Omnibus database showed that BD could reduce the expression of DAP3 in the luminal A subtype of breast cancer (MCF7 cells), indicating that DAP3 might be a possible target for BD intervention in breast cancer." (PMID 38352299, 2023). "Therefore, it was speculated that BD could downregulate the expression of DAP3 through the PI3K/AKT signaling pathway, thus inhibiting the proliferation of breast cancer." (PMID 38352299, 2023).
gastric cancer (6 papers, 2017 to 2025). A primary or metastatic malignant neoplasm involving the stomach. "Research has found that high expression of DAP3 in gastric cancer is associated with better prognosis, suggesting its potential as a prognostic biomarker." (PMID 40371222, 2025). "DAP3 exerts a pivotal role in cell apoptosis, an important mechanism regulating the proliferation of malignant tumors; therefore, it was suggested that DAP3 deficiency might be related to the progression of gastric cancer." (PMID 38352299, 2023). "Moreover, Death-associated protein-3 (DAP-3) was also found to be a useful predictive biomarker for predicting response to NAC in gastric cancer patients treated." (PMID 27802185, 2017). "Therefore, it was speculated that targeting LGR5 could be a promising therapeutic strategy to improve chemoresistance in DAP3-deficient gastric cancer cells." (PMID 38352299, 2023). "Another study on gastric cancer also found higher levels of DAP3 expression in highly or moderately differentiated tumors by RT-PCR and immunohistochemistry." (PMID 38352299, 2023). "Downstream LGR5 expression was upregulated in DAP3-deficient stomach cancer cells, while down-regulation of LGR5 re-sensitized DAP3-deficient stomach cancer cells to 5-FU and oxaliplatin." (PMID 38352299, 2023). "Another gastric cancer study found that LGR5-KD could re-sensitize DAP3-depleted gastric cancer cells to 5-fluorouracil (5-FU) and oxaliplatin." (PMID 39821694, 2025). "According to T-staging and TNM staging, the expression level of DAP3 showed a decreasing trend in more advanced tumors, which indicated that DAP3 expression correlated significantly and negatively with the prognosis of gastric cancer." (PMID 38352299, 2023). "This suggests that the roles of MRPL39,MRPS5,and DAP3 in gastric cancer may be complex." (PMID 40371222, 2025). "When gastric carcinoma cells were treated with certain concentrations of recombinant human tumor necrosis factor alpha (rhTNF-α) and 5-fluorouracil (5-FU), the proliferation of both BGC-823 and HGC-27 cells was suppressed; meanwhile, DAP3 expression was detected in the treated cell lines." (PMID 38352299, 2023).
glioblastoma (6 papers, 2015 to 2023). The most malignant astrocytic tumor (WHO grade IV). "Meanwhile, silencing of DAP3 in glioblastoma cells attenuated migration." (PMID 38352299, 2023). "DAP3 is highly expressed in pancreatic cancer, glioblastoma multiforme, advanced stage thymomas; and in non-epithelial derived tumors, Burkitt Lymphoma, and in a subtype of acute lymphoblastic leukemia according to an earlier study." (PMID 38352299, 2023).
hepatocellular carcinoma (5 papers, 2022 to 2025). A malignant tumor that arises from hepatocytes. "Here, we found that the mitochondrial protein death-associated protein 3 (DAP3) is localized to mitochondria and promotes the progression of hepatocellular carcinoma (HCC) by regulating mitochondrial function." (PMID 39080251, 2024). "A previous study has established a prognostic risk model for hepatocellular carcinoma (HCC) based on five ARGs (BAK1, SPP1, BSG, PBK, and DAP3)." (PMID 40901678, 2025).
glioma (4 papers, 2015 to 2023). A benign or malignant brain and spinal cord tumor that arises from glial cells (astrocytes, oligodendrocytes, ependymal cells). "In addition, subsequent upregulation of DAP3 might cause the resistance of glioma cells to radiotherapy and chemotherapy." (PMID 38352299, 2023). "The authors hypothesized that integrin activation increases DAP3 transcript levels to enhance glioma cell migration, and secondary activation might alter the function of DAP3, reducing its pro-apoptotic activity." (PMID 38352299, 2023). "When the glioma cell line, T98G, was placed on laminin and extracellular matrix (ECM), both the mRNA expression and protein levels of DAP3 were upregulated and the cell resistance to apoptosis was enhanced." (PMID 38352299, 2023).
lung adenocarcinoma (4 papers, 2015 to 2023). A carcinoma that arises from the lung and is characterized by the presence of malignant glandular epithelial cells. "We have previously reported that the mitochondrial ribosomal protein death-associated protein 3 (DAP3) regulates the radioresistance of human lung adenocarcinoma (LUAD) cell lines A549 and H1299." (PMID 37023702, 2023). "Here, we investigated the involvement of mitochondrial dynamics and mitochondrial ribosome protein death-associated protein 3 (DAP3) in the modulation of cellular radiation response by Poly(I:C) in A549 and H1299 human lung adenocarcinoma cell lines." (PMID 33401559, 2021). "We investigated whether DAP3 is involved in the more-than-additive increase in the death of human lung adenocarcinoma cells caused by cotreatment with Poly(I:C) and IR." (PMID 33401559, 2021). "In conclusion, we show that the downregulation of DAP3 protein expression by Poly(I:C) contributes to the more-than-additive effect of cotreatment with Poly(I:C) and IR on cell death in human lung adenocarcinoma cells." (PMID 33401559, 2021). "We next examined the role of DAP3 in the radiation response of human lung adenocarcinoma cells using DAP3-knockdown cells." (PMID 33401559, 2021). "Collectively, these results indicate that DAP3 is involved in radioresistance of human lung adenocarcinoma cells." (PMID 33401559, 2021). "Together, our findings suggest that RLR agonist Poly(I:C) modulates the cellular radiation response of lung adenocarcinoma cells by downregulating DAP3 expression." (PMID 33401559, 2021). "We then investigated DAP3 expression in A549 and H1299 human lung adenocarcinoma cells treated with Poly(I:C) and/or IR." (PMID 33401559, 2021). "Therefore, it is likely that DAP3 controls the radioresistance of lung adenocarcinoma cells in a mitochondria fission-independent manner." (PMID 33401559, 2021). "To address this hypothesis, we investigated the relationship between mitochondrial dynamics, DAP3, and the modulation of the cellular radiation response by Poly(I:C) in human lung adenocarcinoma cells." (PMID 33401559, 2021). "Although this study depicted the involvement of DAP3 in radioresistance of human lung adenocarcinoma cells, the mechanism by which DAP3 regulates radioresistance remains unclear." (PMID 33401559, 2021). "In addition, the present results highlighting the importance of DAP3 in the cellular radiation response of human lung adenocarcinoma cells improve our understanding of DAP3-mediated radioresistance mechanisms and have implications on the efficacy of radiation therapy for lung adenocarcinoma." (PMID 33401559, 2021). "In addition, siRNA experiments showed that DAP3, and not mitochondrial dynamics, is involved in the resistance of lung adenocarcinoma cells to IR-induced cell death." (PMID 33401559, 2021). "However, siRNA experiments revealed that DAP3, but not mitochondrial dynamics, regulates radioresistance and is involved in the more-than-additive effect of cotreatment with Poly(I:C) and IR on cell death in human lung adenocarcinoma cells." (PMID 33401559, 2021).
osteosarcoma (4 papers, 2014 to 2024). A usually aggressive malignant bone-forming mesenchymal neoplasm, predominantly affecting adolescents and young adults. "This study characterised the expression of LKB1 to be critical for TRAIL-induced apoptosis mediated by DAP3 on the basis of knock-down studies in osteosarcoma cells." (PMID 25883535, 2015). "A previous study showed that DAP3 can be phosphorylated by AKT in osteosarcoma cells." (PMID 39080251, 2024). "Besides, in osteosarcoma cells, LKB1 is critical for TRAIL and death associated protein 3 (DAP3)-induced cell apoptosis, while K78M LKB1, a kinase dead mutant, can inhibit DAP3-induced cell apoptosis in these cells." (PMID 25244018, 2014). "Therefore, LKB1 and DAP3 are thought to be promising targets for osteosarcoma therapy." (PMID 38352299, 2023). "In a similar fashion, DAP3 was found to mediate interactions between FADD and LKB1 interacting protein 1 (LIP1) in human osteosarcoma cells, which anchors LKB1 to the cytoplasm." (PMID 25883535, 2015).
colorectal cancer (3 papers, 2018 to 2025). A primary or metastatic malignant neoplasm that affects the colon or rectum. "In colorectal cancer tissues, the transcription and protein levels of DAP3 (also known as MRPS29) and DELE1 are significantly higher than those in normal tissues." (PMID 40371222, 2025). "Similarly, for PYY-CKAP2 and SDCBP2-DAP3 gene pairs, up-regulation of CKAP2, DAP3 and down-regulation of PYY, SDCBP2 contribute to the reversal REO in colorectal cancer samples." (PMID 29378509, 2018).
liver cancer (3 papers, 2023 to 2025). An epithelial or non-epithelial malignant neoplasm that arises from the liver. "A larger sample size and more experimental validation would strengthen the conclusions and help establish more robust evidence for the role of DAP3 in liver cancer." (PMID 40051634, 2025). "Although previous studies have reported on DAP3 expression and its basic functions in liver cancer, this study provides new insights from the perspective of the immune microenvironment and prognostic modeling, thereby expanding the functional understanding of DAP3 within the tumor microenvironment." (PMID 40051634, 2025). "Although DAP3 shows promising potential as a biomarker and therapeutic target in liver cancer, the specific pathway for its clinical translation remains unclear." (PMID 40051634, 2025). "Data from screening cancer growth-related genes by mining the genome-wide CRISPR-Cas9 knockdown database showed that DAP3 gene knockdown could inhibit the growth of JHH-5, HuH-1, SNU398, and other liver cancer cell lines." (PMID 37415742, 2023).
colon adenocarcinoma (2 papers, 2022 to 2023). "Bevacizumab functions as an inhibitor of tumor angiogenesis; therefore, a panel of biomarkers was applied to investigate the correlation between DAP3 and neovascularization in the TCGA-Colon Adenocarcinoma dataset." (PMID 38352299, 2023).
esophageal squamous cell carcinoma (2 papers, 2022 to 2023). Esophageal squamous cell carcinoma (ESCC) is a type of esophageal carcinoma (EC) that can affect any part of the esophagus, but is usually located in the upper or middle third. "have shown that the subcutaneous injection of a DAP3-depleted esophageal squamous cell carcinoma cell line into mice can lead to the formation of much smaller tumors (when compared with those formed by the injection of control cells)." (PMID 37023702, 2023).
pancreatic cancer (2 papers, 2022 to 2023). "Previous analysis of DAP3 expression in a clinical cohort indicated that DAP3 was highly expressed in pancreatic tumor tissues and was significantly associated with shorter survival." (PMID 38352299, 2023). "Levels of DAP3 transcripts in pancreatic cancer tissues were elevated compared to those in normal tissues Patients with high levels of DAP3 had a significantly shorter overall survival than those with low levels." (PMID 38352299, 2023). "Levels of DAP3 transcripts in pancreatic cancer tissues were elevated compared with those in normal tissues." (PMID 38352299, 2023). "When compared with that in normal tissues, cancer tissues from 223 patients with pancreatic cancer expressed higher levels of DAP3, which did not correlate with DAP1 expression levels." (PMID 38352299, 2023).
papillary carcinoma (2 papers, 2009 to 2023). A malignant epithelial neoplasm characterized by a papillary growth pattern. "The expression of DAP3 also depends on the number of mitochondria in aerobic thyroid tumors, papillary thyroid carcinoma, and oncological potential undefined thyroid carcinoma." (PMID 38352299, 2023). "When thyroid tumors have a rich mitochondrial content, whether they belong to the oxyphilic tumor categories, to the papillary carcinomas or UMP type, DAP3 overexpression is dependent on the cell mitochondrial content." (PMID 38352299, 2023).
thyroid tumor (2 papers, 2009 to 2023). A benign or malignant neoplasm affecting the thyroid gland. "The mitochondrial role of DAP3 was also investigated in the thyroid tumours presenting various mitochondrial contents." (PMID 19536094, 2009). "Exploring the thyroid tumours, we found that DAP3 mRNA and protein expression is upregulated in tumours presenting a mitochondrial biogenesis compared with the normal tissue." (PMID 19536094, 2009). "In this publication, we show a significant overexpression of DAP3 mRNA in three types of thyroid tumour (FTA, PTC and OTT) compared with their NT tissue counterparts." (PMID 19536094, 2009). "We studied the expression of the DAP3 mRNA and protein in thyroid tumours using quantitative real-time polymerase chain reaction (qRT–PCR) and immunohistochemistry (IHC) techniques." (PMID 19536094, 2009).
asthma (1 paper, 2021). "DAP3 mediates IFN-γ-induced cell death and is strongly associated with asthma, especially in patients with high serum IgE." (PMID 34975829, 2021).
ataxia telangiectasia (1 paper, 2023). Ataxia-telangiectasia is the association of severe combined immunodeficiency (affecting mainly the humoral immune response) with progressive cerebellar ataxia. "In terms of mitochondrial ribosomal protein S29 (death-associated protein 3, DAP3), Henning has reported that the overexpression DAP3 can confer radioresistance to ataxia-telangiectasia cells exhibiting high radiosensitivity." (PMID 37023702, 2023).
colon cancer (1 paper, 2023). "Research by Sui and his coworkers demonstrated that the expression of DAP3 was increased in colon cancer tissue compared with that in normal adjacent tissue at the mRNA and protein level." (PMID 38352299, 2023). "Knockdown of DAP3 and DELE1, respectively, in colon cancer CRC cell lines sensitized the cells to 5-FU, Methotrexate, and Docetaxel, and cells with simultaneous knockdown of DAP3 and DELE1 were markedly sensitive to all the drugs tested, compared with the single knockdown lines and the controls." (PMID 38352299, 2023).
deafness (1 paper, 2025). An inherited or acquired condition characterized by the complete loss of the ability to hear from one or both ears. "Variants in the gene encoding 12S rRNA (MT-RNR1, MIM: 561000) are associated with sensorineural, non-syndromic deafness, suggesting that, as a result of their reduced abundance, altered MRPS7 and 12S rRNA interactions might account for the SNHL in individuals with variants in DAP3." (PMID 39701103, 2025).
Encephalopathy (1 paper, 2025). Encephalopathy is a term that means brain disease, damage, or malfunction. "Mitochondrial ribosomal proteins such as MRPL49 (mitochondrial ribosomal protein L49) and DAP3 (death associated protein 3) have been associated with encephalopathy and progressive SNHL." (PMID 41191133, 2025).